ATF6 (activating transcription factor 6)
Diseases named in the same sentence as ATF6 in open-access papers (continued):
Sharing a sentence is not in itself a finding about the gene and the disease.
cancer (continued). "We have also confirmed this selective activation of PERK and IRE1α, but not of ATF6 is not unique to MM but applies to other cancer cells treated with 2P‐Im (data not shown)." (PMID 37149844, 2023). "However, ATF6 inhibition by ceapinA7 still reduced BRCA-1 expression level and increased γH2AX and CHOP expression level also in cancer cells treated by Thapsigargin at low dose (10 nM)." (PMID 35752616, 2022). "Various studies have indicated that ERS is associated with cancer, and many ERS-related proteins, such as glucose-regulated protein 78 (GRP78)/binding protein (BiP), activating transcription factor 6 (ATF6), and inositol-requiring protein 1 (IRE1), are involved in many types of cancer." (PMID 35211240, 2022). "ATF6 plays a significant part in activating the unfolded protein response (UPR) during endoplasmic reticulum stress, which has been reported to be promotive in cancer tumorigenesis and metastasis." (PMID 33178587, 2020). "ATF6 induces the expression of RHEB, which activates mTOR signaling and renders therapeutic resistance to dormant cancer cells, suggesting targeting ATF6 might be one of the valuable therapeutic strategies." (PMID 31739582, 2019). "This is the first study that provides the link between ATF6 and CIP2A in cancer." (PMID 30063110, 2018). "Three sensors of ER stress - activating transcription factor 6 (ATF6), inositol-requiring enzyme 1 (IRE1) and protein kinase RNA-like endoplasmic reticulum kinase/ eukaryotic translation initiation factor-2α kinase 3 (PERK) - initiate the UPR in cancer cells." (PMID 28499449, 2017). "In addition, the expression levels of other genes related to ER stress, such as IRE1, ATF6, PERK and XBP1 also increased following NASTRp treatment in human cancer cells." (PMID 25897662, 2015). "We report that cancer induced liver Bip/GRP78 and IRE1α while suppressing the expression of ATF6." (PMID 25789991, 2015). "Here we report that the three master regulators of the UPR, IRE1α, PERK and ATF6α, mediate transcriptional regulation of VEGFA under ER stress which occurs during normal development of labyrinthine trophoblast cells in the placenta as well as in cancer cells." (PMID 20221394, 2010). "However, high ATF6 level did not correlate with the overall survival of patients with biliopancreatic carcinoma, prostate, and colon cancers, although it was a predictor of a shorter recurrence time." (PMID 40650182, 2025). "UPR effectors, including ERN1 (IRE1α), ATF6, and PERK (EIF2AK3), dissociate from HSPA5 (GRP78) and activate their respective canonical targets (XBP1s, ATF6α, and ATF4); subsequently trigger transcriptional reprogramming that promotes the survival of cancer cells under ER stress." (PMID 40821803, 2025). "Thus, our findings reveal de novo TPD52/ATF6‐mediated signaling activated during ER stress, which is abrogated by APCCdc20‐mediated polyubiquitination of TPD52 at K179, and thereby suggests synergistic strategies for cancer therapy." (PMID 39401430, 2024). "Cancer cells under endoplasmic reticulum (ER) stress activate the UPR, which is composed of the binding immunoglobulin protein (BiP) and three major branch pathways, including the PRKR-like ER kinase (PERK), inositol-requiring enzyme 1 (IRE1), and activating transcription factor 6 (ATF6) pathways." (PMID 39420837, 2024). "Notably, ATF6α pathway of ER stress/UPR enhances cell survival against cancer therapy, suggesting that TIS may be mediated through ER stress, particularly via the ATF6α pathway." (PMID 39466820, 2024). "Hence, we speculate that ATF6 and PERK may constitute another potential pathway regulated by AGR2 that influences cancer cell progression and resistance to sorafenib." (PMID 36899352, 2023). "We also investigated whether expressing c-ATF6 affected cancer cell migration and invasion in vitro, and we found that expressing c-ATF6 but not full-length ATF6 significantly enhanced cancer cell migration and invasion." (PMID 37390992, 2023).
cancer (continued). "In this study, we demonstrated that the exposure of cancer cells to sublethal doses of curcumin could promote DDP chemotherapeutic efficiency against NSCLC cells, in which the ER stress pathway mediated by the CHOP, ATF6, and caspase-4 plays an important role." (PMID 35754693, 2022). "Conversely, ATF6-α nuclear translocation was not apparent in RPE-1 non-cancer cells." (PMID 34740374, 2021). "We further showed that the ablation of ATF6 or inactivation of EGF signaling are promising strategies to break the interplay between dormant cancer cells and their microenvironment, thereby inhibiting the angiogenesis-mediated awakening of dormant cancer cells." (PMID 32630838, 2020). "In summary, ATF6α serves as an important homeostatic regulator operating in cell- and tissue-specific contexts, and aberrant ATF6 signalling may promote pathogenesis of diverse disease states, including cancer." (PMID 29801500, 2018). "However, as ER stress response effectuates through the independent activation of IRE1, PERK, and ATF6 pathways along with added signaling regulation and crosstalk, it is imperative to understand the role of individual arm of the UPR in distinct models of cancer cachexia." (PMID 31817027, 2019). "Indeed, analyses of the TCGA-KIRC cohort of ccRCC patients via the Gepia2 cancer database (RCC biopsies of the patients) showed that VHL and PBRM1 expressions correlate with ERN1, EIF2AK3 and ATF6, whereas BAP1 does not correlate with any of the ER stress mediators." (PMID 36902344, 2023).
infection (88 papers, 2007 to 2026). The state of being infected such as from the introduction of a foreign agent such as serum, vaccine, antigenic substance or organism. "To test if SEL1L dependent ERAD contributes to loss of ATF6-FL during infection, we next compared ATF6 processing in HEK293-FcγR cells that were treated with non-targeting or SEL1L-targeting siRNA." (PMID 34635501, 2021). "Interestingly, the involvement of ATF6 in the protection of cells is associated with the ability of pathogenic Mtb to protect cells at an early stage of infection." (PMID 37800958, 2023). "The two other arms of the UPR, the IRE1α and ATF6 pathways, have mostly been implicated in the restoration of cellular homeostasis under stress conditions and, in the context of infection, may play a supportive role in viral protein production." (PMID 34834970, 2021). "The activation of the PERK, IRE1α, and ATF6 signaling pathways following PTV-GXLZ2024 infection was investigated." (PMID 41012628, 2025). "To understand the activation of UPR by any of these pathways, we used confocal microscopy and quantified the translocation of downstream transcription factors, such as XBP1, ATF4, and ATF6, inside the nucleus upon infection." (PMID 40272166, 2025). "We did not observe any changes in the induction of ER-stress response genes XBP1s or ATF6 after infection or treatment with tunicamycin." (PMID 39804047, 2025). "We observed atf6 activation in parallel with deceleration of mosquito mortality at 24 h post-infection, so it is possible that ATF6 mediates tolerance to infection by coordinating the repair of S. marcescens-induced damages." (PMID 41218768, 2025). "In our data, we observed an increase in atf6 transcripts concomitant with a decrease in bip transcripts at 24 h post-infection." (PMID 41218768, 2025). "A previous study demonstrated that PPRV infection can selectively activate the ATF6 branch of the UPR in Vero cells." (PMID 38812563, 2024). "It has also been found that the Seneca valley virus (SVV), an important emerging porcine virus, promotes autophagy and SVV production by inducing the PERK and ATF6 pathways of UPR upon its infection." (PMID 39227990, 2024). "The subsequent objective is to investigate the potential for ATF6 pathway activation following a CDVOnd infection." (PMID 39772156, 2024). "This conclusion was based upon the fact that molecules such as BiP and PDIA4 had their mRNA levels significantly reduced in ATF6α knockout cells upon infection." (PMID 37434252, 2023). "The ATF6α sensor is robustly activated during infection while the IRE1α-XBP1 branch is down-regulated." (PMID 37434252, 2023). "Cell lysates were harvested at 0, 3, 6, 12, 24 and 48 h post infection (hpi) and we detected that both virus’ strains can induce noticeable increase in ATF6α reporter activity during the course of infection, with distinguishable intensities." (PMID 37434252, 2023). "In this study, we found that the expression levels of proteins in the ER stress pathway, including PERK and ATF‐6, were significantly higher in HepG‐2 cells infected with Ad‐Vp3 than cells infected with Ad‐Mock when tested at 12 and 24 h post‐infection." (PMID 36515089, 2023). "CVB3 was also shown to trigger ER stress: upon CVB3 infection, ATF6 and Xbp1 were activated via protein cleavage and mRNA splicing, respectively, but all of these changes occurred at the late stages of infection (12 h post-infection, hpi)." (PMID 36366584, 2022). "In contrast, no changes were observed in the survival of ces-2(gk1020), ztf-11(ok646), or atf-6(ok551) animals fed E. faecium before infection." (PMID 35263319, 2022). "Only ATF6 activation is detected during early infection while the activity of the eIF2alpha/ATF4 signaling is increased at the final stage of HSV-1 replication, suggesting that HSV-1 disarms the unfolded protein response in the early stages of infection." (PMID 35336954, 2022).
infection (continued). "Together, these results suggest that significant inhibition of ZIKV replication can be achieved by attenuating PERK and ATF6 activation and increased IRE1α phosphorylation at an early time of infection." (PMID 34106769, 2021). "ATF6 mRNA expression was strongly increased 12 h after infection with NOX5-β adenovirus compared with the GFP-infected group." (PMID 33572841, 2021). "Our previous analysis on L.p.–mediated manipulation of the UPR revealed a dynamic processing of full length ATF6 protein levels during infection." (PMID 34635501, 2021). "Nevertheless, the significant reduction in virus titers indicates a role of the ATF6 pathway in late phase of infection." (PMID 34106769, 2021). "ATF6, on the other hand, is required for late phase of infection, as demonstrated by the significantly high degree of p90ATF6 disappearance and the ability of Ceapin-A7 to reduce virus titers at 48 and 72 hpi." (PMID 34106769, 2021). "Many viruses are known to use different mechanisms to modulate the three UPR branches, including the PERK-, IRE1- and ATF6-mediateing signaling pathways, to benefit their productive infection." (PMID 33919712, 2021). "The expression levels of phosphorylated IRE1α and PERK as well as of cleaved ATF6 were significantly increased in a parasite burden- and infection time-dependent manner." (PMID 34895315, 2021). "Dengue virus also temporally regulate the UPR by triggering transient PERK-eIF2α phosphorylation during the early phase and IRE1α-XBP1 and ATF6 during mid-phase and late phase of infection." (PMID 34106769, 2021). "Detection of ATF6-Nt demonstrates that the ATF6 pathway is also activated during the course of infection." (PMID 34138976, 2021). "In MHV infected cells, ATF6 was processed to its active form at 7 h after infection, but both full-length ATF6 and active ATF6 disappeared at the later stage of infection." (PMID 35003039, 2021). "On the other hand, infection in neuroblastoma cells leads to high levels of ATF6 activation, with transient eIF2α phosphorylation, while XBP1 splicing seems to have no role in viral replication." (PMID 32106582, 2020). "To better characterize the underlying mechanism of the ER stress response induced by HRV16, we examined the effect of infection on the three ER stress pathways (ATF6, PERK and IRE1)." (PMID 30717233, 2019). "Collectively, these data demonstrated that the ATF6 pathway was activated in H1-HeLa cells upon HRV16 infection." (PMID 30717233, 2019). "Conversely, WNVKUN infection, which also induces activation of the ATF6 branch of the UPR at 12–18 h.p.i., showed decreased titers in ATF6-/- MEFs30,31." (PMID 31467282, 2019). "The level of full-length ATF6 (ATF6-FL) was gradually decreased at late infection time in HeLa, Cal27, A549, H1299, Huh7, and 293T, but not in HN13 and HepG2." (PMID 31767828, 2019). "Compared with cells mock-infected with TMUV, expression of ATF6-induced chaperones was upregulated from 12 h to 24 h post-infection and then returned to the level of the mock control." (PMID 30670030, 2019). "According to our data, ATF6 expression and ATF6-mediated regulation of chaperones fluctuated from 12 h to 48 h post-infection." (PMID 30670030, 2019). "The PERK arm is activated early in DENV infection, followed by IRE1-XBP1 mid-infection, and ATF6 later during the infection." (PMID 31461934, 2019). "An N-terminal intermediate p45 fragment (N-45) derived from ATF6 was detected during EV-A71 infection, and this fragment migrated more rapidly than the p50 fragment produced by DTT treatment." (PMID 29386036, 2018). "Together, these observations provide strong direct evidence that 3Cpro is the proteinase responsible for cleavage near the C-terminus of ATF6 during infection." (PMID 29386036, 2018). "Our data also agree with published reports showing that the TGF-beta pathway upstream of shn and the Atf6 transcription factor are important to survive infection." (PMID 29394281, 2018).
infection (continued). "In the present study, we further examined the role of ATF6 during EV-A71 infection, including its cleavage process and its role in viral life cycle." (PMID 29386036, 2018). "We examined the role of ATF6 during EV-A71 infection, including its cleavage process and its role in viral life cycle by silencing or overexpressing ATF6." (PMID 29386036, 2018). "Viruses differ in their ability to activate the three arms of UPR transmembrane sensors, PERK, IRE1 and ATF6, some activating all three while some one or two during their infection." (PMID 26907328, 2016). "In contrast, ATF6 cleavage is observed by MHV infection, although both the full-length and the cleaved form of ATF6 decreased significantly at late stage of infection due to sustained translational attenuation." (PMID 27384577, 2016). "The levels of pPERK and cleaved ATF6 remained almost the same between control and Yip1A-knockdown cells during infection." (PMID 25742138, 2015). "Infection with siATF6 adenovirus resulted in ~79 and 74 % reduction in ATF6 mRNA in ATDC5 cells and C3H10 cells, respectively." (PMID 26374329, 2015). "To further understand the role of ATF6 during infection with L. pneumophila we performed qRT–PCR to determine ATF6 transcript abundance." (PMID 26219498, 2015). "Infection of Huh7 with JFH1 provoked an acute ER stress response concomitant with ATF6 cleavage, XBP1 splicing and PERK phosphorylation at 6–9 dpi followed by a chronic and milder ER stress with a diminished CHOP level at 15–22 dpi." (PMID 24904547, 2014). "For instance, one report on DENV describes early PERK activation followed by inhibition, XBP1 induction mid-infection and ATF6 activation late in infection." (PMID 24904537, 2014). "The infection of cells by several viruses has been shown to activate the ATF6 pathway, including the Tick-borne encephalitic virus, African swine fever virus (ASFV), West Nile virus (WNV), and HCV." (PMID 24987391, 2014). "For this, HEK293 cells were infected with CHIKV or SINV at an MOI of 1 and at indicated time points (0, 3, 6, 12, 24 and 48 h) post infection, cells were harvested, lysed and subjected to protein and RNA analysis for the component genes of ATF-6 pathway." (PMID 23356742, 2013). "The protein levels of both trans-membrane and cleaved cytosolic ATF-6 were increased throughout the infection time course compared to the uninfected control (0 h)." (PMID 23356742, 2013). "We previously demonstrated the induction of the IRE1-XBP1 pathway 12–36 h post-infection (p.i) and the transient activation of the ATF6 pathway late in DENV-2 infection." (PMID 22675522, 2012). "We assessed the presence of this nuclear form of ATF6 as a marker of its activation during infection by Dengue virus." (PMID 17888185, 2007). "However, the optimal strategy would depend on the specific pathogen and infection context, requiring a detailed understanding of how individual bacterial species exploit ATF6 signaling." (PMID 41546510, 2026). "Alternatively, ATF6 inhibitors like Ceapins could disrupt pathogen‐induced ATF6 signaling that promotes infection establishment." (PMID 41546510, 2026). "ATF6 activators such as Compound 147 could enhance host ER folding capacity and stress resistance, potentially improving immune cell function during infection." (PMID 41546510, 2026). "ATF6 levels remained unchanged across all three cell lines during the infection time course." (PMID 40843354, 2025). "The ATF6 gene was significantly inhibited during the late infection (36 and 48 hpi)." (PMID 40248709, 2025). "As expected, LV-ATF6 infection successfully increased the level of c-ATF6 protein." (PMID 40860156, 2025). "To determine whether Atf6–/– mice had infection, inflammation, scarring, or tissue damage in the ME, we analyzed prepared histologic sections of the ears from 2-month-old Atf6–/– mice." (PMID 39570676, 2025). "It suggests that the ATF6 pathway is required for the late phase of infection." (PMID 40248709, 2025).